DMD (dystrophin)
Diseases named in the same sentence as DMD in open-access papers (continued):
Sharing a sentence is not in itself a finding about the gene and the disease.
cataract (1 paper, 2019). Partial or complete opacity of the crystalline lens of one or both eyes that decreases visual acuity and eventually results in blindness. "However, deflazacort still shows potent GR transactivation, and recent DMD trials report increased cataracts, cushingoid features, and growth delay with deflazacort versus prednisolone." (PMID 30745312, 2019).
Charcot-Marie-Tooth disease type 1A (1 paper, 2023). Charcot-Marie-Tooth disease type 1A (CMT1A) is a type ofinherited neurological disorder that affects the peripheral nerves. "A Czech patient had a phenotype caused by the combination of a point mutation in the DMD gene and a duplication of the PMP22 gene causing CMT1A (Charcot-Marie-Tooth disease type 1A), and a Chinese patient had a phenotype caused by a duplication of the PMP22 gene and a DMD deletion." (PMID 37569734, 2023).
chronic kidney disease (1 paper, 2025). Impairment of the renal function secondary to chronic kidney damage persisting for three or more months. "Indeed, progressive muscle degeneration in Duchene’s muscular dystrophy, caused by mutations in DMD, seems to be associated to subclinical kidney injury and the subsequent development of chronic kidney disease in paediatric patients." (PMID 40173198, 2025).
coloboma (1 paper, 2012). An abnormality in which a part of a structure in one or both eyes is missing. "We report a 44-year-old healthy father of a 10-year-old daughter with bilateral coloboma and hearing loss, but without muscle weakness, in whom a whole-genome CGH revealed a deletion of exons 38–44 in the dystrophin gene." (PMID 22707356, 2012).
colon cancer (1 paper, 2023). "The univariate and multivariate analyses also demonstrated the independent prognostic value of RAB3C combined with dystrophin in colon cancer patients." (PMID 36652260, 2023). "Here we demonstrate that RAB3C dominates the drug resistance and exocytosis in colon cancer, and that dystrophin also plays a role." (PMID 36652260, 2023). "To identify potential strategies for further application in the clinic, we compared the IC50 of several PIK3CA inhibitors and the endogenous levels of RAB3C and dystrophin in the colon cancer cell panel." (PMID 36652260, 2023). "Thus, detecting the RAB3C/dystrophin expression in colon cancer can reflect the patient's prognosis, as well as his/her response to targeted therapy applications." (PMID 36652260, 2023). "The authors found that RAB3C overexpression induces dystrophin expression to promote vesicle formation and packaging for increased exocytosis, is related to drug resistance and is correlated with PIK3CA/KRAS mutation status in colon cancer." (PMID 36652260, 2023).
diffuse large B-cell lymphoma (1 paper, 2023). "DMD gene expression was increased in primary tumors in two out of 25 comparisons, namely in primary thyroid carcinoma and diffuse large B-cell lymphoma, with LogFC values of 0.9 and 4.8, respectively." (PMID 36900171, 2023).
Down syndrome (1 paper, 2023). "A similar case with the concurrent identification of a very mild myopathic phenotype caused by DMD exon 15 skipping in a patient with Down syndrome has been recently reported." (PMID 37298193, 2023).
endometriosis (1 paper, 2021). The growth of functional endometrial tissue in anatomic sites outside the uterine body. "MYLK, ACTA2 and DMD were associated with six kinds of drugs for endometriosis, and four of which had been validated by researchers, ACACB and IGHM were associated with eight kinds of drugs, three of which had been approved by researchers." (PMID 34409913, 2021).
Eosinophilia (1 paper, 2008). "Eosinophilia has also been reported as a prominent feature of the necrotic phase in dystrophin-deficient mdx mice." (PMID 19015733, 2008).
gastric adenocarcinoma (1 paper, 2017). "On the contrary, miR-486 plays a pro-apoptotic tumor-suppressor role, and its high expression was associated with a good prognosis in gastric adenocarcinoma; however, miR-486 over expression in dystrophin-deficient mice was also observed to reduce PTEN expression." (PMID 28052756, 2017).
head and neck squamous cell carcinoma (1 paper, 2025). A squamous cell carcinoma that arises from any of the following anatomic sites: lip and oral cavity, nasal cavity, paranasal sinuses, pharynx, larynx, and salivary glands. "This study investigates the prognostic and biological significance of DMD expression in head and neck squamous cell carcinoma (HNSCC)." (PMID 40155657, 2025). "In our own preliminary study on the effect of high versus low DMD gene expression on survival outcomes across all cancers, we found that high DMD expression might be associated with longer head and neck squamous cell carcinoma (HNSCC) survival times." (PMID 40155657, 2025).
Hengel-Maroofian-Schols syndrome (1 paper, 2024). "This translocation completely disrupts the Dp472 muscle isoform of the DMD gene and the BCAS3 gene, which is an important cytoskeletal protein during embryogenesis, angiogenesis, and tumorigenesis, and has been recently identified to cause the autosomal, recessive Hengel–Maroofian–Schols syndrome." (PMID 39063034, 2024).
hereditary neuropathy with liability to pressure palsies (1 paper, 2024). Hereditary neuropathy with liability to pressure palsies (HNPP) is an inherited peripheral nerve disorder characterized by recurrent mononeuropathy usually triggered by minor physical activities. "One exception was about a female patient diagnosed with hereditary neuropathy with liability to pressure palsies (HNPP, caused by 17p12 microdeletion) who was incidentally found having complex non-contiguous fragments involving 3′-terminal partial exons of DMD." (PMID 39117454, 2024).
Huntington disease (1 paper, 2019). Huntington disease (HD) is a rare neurodegenerative disorder of the central nervous system characterized by unwanted choreatic movements, behavioral and psychiatric disturbances and dementia. "Even though as little as 4% recovery of dystrophin expression restores significant muscle function to treat DMD24,25, a higher modification rate is needed in other cases, such as Huntington disease, which requires a 40% reduction of mutant Huntingtin for clinical improvement." (PMID 31636954, 2019).
hyperhomocysteinemia (1 paper, 2010). A serious metabolic condition caused by mutations in the MTHFR gene, medications, or nutritional deficiency. "Moreover, it has been observed that imprinted gene H19 is hypermethylated, not hypomethylated, in brain and aorta of hyperhomocysteinemic mice, although the effect of hyperhomocysteinemia on H19 DMD methylation was tissue-specific in these mice." (PMID 20300621, 2010).
hyperlipidemia (1 paper, 2024). "While these may be caused by steroids, hyperlipidemia has been documented following the loss of a single dystrophin allele, which does not cause muscle wasting in carrier individuals." (PMID 39716324, 2024).
ischemic stroke (1 paper, 2022). A stroke disorder caused by obstruction of blood flow to the brain, due to thrombotic (local blood clot formation) or embolic (due to a blood clot or other material traveling from another site) event. "However, after ischemic stroke, α-syntrophin and dystrophin are retained in perivascular membranes, indicating that other mechanisms must be responsible for the loss of perivascular AQP4." (PMID 35163040, 2022).
kidney failure (1 paper, 2025). An acute or chronic condition that is characterized by the inability of the kidneys to adequately filter the blood. "While we have identified promising potential modifier variants in NFU1, DMD, HPS5, CLDN8 and CLDN17, their functional impact on FHHNC progression towards kidney failure remains to be characterized." (PMID 40173198, 2025).
liposarcoma (1 paper, 2014). A usually painless malignant tumor that arises from adipose tissue. "Specifically, it was found that the mice with the mutation in Dystrophin, Dysferlin and Calpain-3 were susceptible to spontaneous formation of rhabdomyo-, fibro-and liposarcomas derived from skeletal muscle tissue 1–4 (reviewed in 5)." (PMID 24341522, 2014).
low grade glioma (1 paper, 2022). A grade I or grade II glioma arising from the central nervous system. "We undertook a detailed bioinformatic analysis of low-grade glioma (LGG) bulk RNAseq data to characterise the association between DMD expression and LGG survival outcomes." (PMID 35217778, 2022).
malaria (1 paper, 2024). Malaria is a serious and sometimes fatal disease caused by a parasite that commonly infects a certain type of mosquito which feeds on humans. "GO and KEGG enrichment analyses showed candidate genes were associated with exocytic vesicle membrane, synaptic vesicle membranes, glycoprotein complex, dystrophin-associated glycoprotein complex and malaria." (PMID 38687434, 2024).
malnutrition (1 paper, 2021). Inadequate nutrition resulting from poor diet, malabsorption, or abnormal nutrient distribution. "Serological tests showed that the levels of serum albumin (ALB) and prealbumin (PA) were significantly reduced in DMD-delE51 pigs, indicating malnutrition." (PMID 34266495, 2021). "Indeed, measurement of muscle glycogen and triglyceride supported that malnutrition occurred in DMD-delE51 pigs (***P < 0.001, *P < 0.05)." (PMID 34266495, 2021). "We found that genetic disruption of dystrophin expression led to morphological gastrointestinal tract alterations, weakened the gastrointestinal tract digestion and absorption capacity, and eventually led to malnutrition and gastric dysfunction in the DMD pigs." (PMID 34266495, 2021).
mesothelioma (1 paper, 2026). A usually malignant and aggressive neoplasm of the mesothelium which is often associated with exposure to asbestos. "DMD alterations are also less frequent in mesothelioma, and it has a low tumour mutation burden." (PMID 40832923, 2026).
metachromatic leukodystrophy (1 paper, 2025). A rare lysosomal storage disorder characterized by intralysosomal accumulation of sulfatides in various tissues, leading to progressive deterioration of motor and neurocognitive function. "For example, gene therapies for diseases such as metachromatic leukodystrophy and DMD gene mutations have been approved for marketing." (PMID 41142719, 2025).
microcephaly (1 paper, 2023). A congenital or acquired developmental disorder in which the circumference of the head is smaller than normal for the person's age and sex. "However, as the proband showed ID with a measured Wechsler test IQ of 41 and microcephaly, it was difficult to determine if ID was also caused by a pathogenic variant of DMD." (PMID 38129582, 2023).
myxofibrosarcoma (1 paper, 2019). A malignant fibroblastic neoplasm arising from the soft tissue. "Here we report that DMD was deleted in 16.5% of pleomorphic sarcomas with complex genomics (myxofibrosarcoma, UPS, LMS, and pleomorphic liposarcoma (pLPS)), 14.2% of GIST, and 20.7% of synovial sarcomas (SS)." (PMID 31266185, 2019).
neuroendocrine tumors (1 paper, 2021). "Furthermore, we observe distinct drivers which are enriched in somatic aberrations in pancreatic (MEN1, ATRX, DAXX, DMD and CREBBP) and midgut-derived neuroendocrine tumors (CDKN1B)." (PMID 34326338, 2021).
oropharyngeal squamous cell carcinoma (1 paper, 2025). "Another study revealed DMD as one of several large common fragile site (CFS) genes to be significantly downregulated in oropharyngeal squamous cell carcinoma (OPSCC); collectively the decreased expression of these genes is associated with an increased occurrence of OPSCC21." (PMID 40155657, 2025).
osteogenesis imperfecta (1 paper, 2023). Osteogenesis imperfecta (OI) comprises a heterogeneous group of genetic disorders characterized by increased bone fragility, low bone mass, and susceptibility to bone fractures with variable severity. "Some studies describe combinations of DMD caused by deletions in the DMD gene with skeletal dysplasia: osteogenesis imperfecta (mutations in the COL1A1 gene) and pseudoachondroplasia (mutation in the COMP gene)." (PMID 37569734, 2023).
Paralysis (1 paper, 2020). Paralysis of voluntary muscles means loss of contraction due to interruption of one or more motor pathways from the brain to the muscle fibers. "We have also developed a temperature-based screening method for synthetic paralysis that can be used to rapidly identify genetic partners of dystrophin." (PMID 32227114, 2020).
Pelizaeus-Merzbacher disease (1 paper, 2007). "This is in line with the findings in studies of deletions of the dystrophin gene in DMD and duplications of PLP1 in Pelizaeus-Merzbacher disease." (PMID 17277737, 2007).
prostate tumors (1 paper, 2017). "Remarkably, we found that DMD expression was decreased in primary prostate tumors and further reduced in metastasis." (PMID 27391342, 2017).
psoriasis (1 paper, 2021). An autoimmune condition characterized by red, well-delineated plaques with silvery scales that are usually on the extensor surfaces and scalp. "IMQ was topically applied on mouse skin to generate psoriasis-like plaque for evaluating the anti-inflammatory activity of DMD." (PMID 34054833, 2021). "We used IMQ to activate macrophages and induce psoriasis-like plaque in mice for evaluating the anti-inflammatory effect of DMD in psoriasis treatment." (PMID 34054833, 2021).
relapsing-remitting multiple sclerosis (1 paper, 2022). The most common clinical variant of multiple sclerosis, characterized by recurrent acute exacerbations of neurologic dysfunction followed by partial or complete recovery. "Antisense Therapeutics has developed an ASO (ALT1102), which is currently in a phase II trial for treatment of patients with relapsing-remitting multiple sclerosis (RRMS) and DMD." (PMID 35482908, 2022).
rheumatic disorder (1 paper, 2020). Inflammatory and degenerative diseases of connective tissue structures, such as arthritis. "VF have been diagnosed as early as 4 to 6 months following GC initiation in children with GC-treated rheumatic disorders and DMD." (PMID 33391179, 2020).
rheumatoid arthritis (1 paper, 2025). A chronic, systemic autoimmune disorder characterized by inflammation in the synovial membranes and articular surfaces. "It is a member of the ‘role of osteoclasts in rheumatoid arthritis signalling’ CP, which was strongly activated in both DMD and BMP4‐stimulated transcriptomes." (PMID 40641092, 2025).
Right ventricular hypertrophy (1 paper, 2020). In this case the right ventricle is more muscular than normal, causing a characteristic boot-shaped (coeur-en-sabot) appearance as seen on anterior- posterior chest x-rays. "We measured ADMA concentration in plasma and lungs, DDAH1 and DDAH2 mRNA and protein expression in the lungs, right ventricular systolic pressure (RVSP), right ventricular hypertrophy by the Fulton index, and cardiomyocyte hypertrophy by dystrophin staining of the heart." (PMID 33281630, 2020).
Rubinstein-Taybi syndrome (1 paper, 2016). A rare malformation syndrome characterized by congenital anomalies (microcephaly, specific facial characteristics, broad thumbs and halluces and postnatal growth retardation), short stature, intellectual disability and behavioral characteristics. "These include single-gene exonic deletions in NRXN1, GRM8, CREBBP (Rubinstein-Taybi syndrome, MIM:180849), KDM4B, and DMD." (PMID 27257017, 2016).
sarcopenia (1 paper, 2024). Progressive decline in muscle mass due to aging which results in decreased functional capacity of muscles. "Consistently with the findings in dystrophic muscle of mdx mice, we found a sharp upregulation of the MYH3/MYH2 ratio in dependent elderly with sarcopenia indicating a shift in myosin isoform expression from the mature to the embryonic form, which recapitulates a feature of DMD." (PMID 38338718, 2024).
Sleep apnea (1 paper, 2019). An intermittent cessation of airflow at the mouth and nose during sleep is known as sleep apnea. "Thus, the high proportion of dystrophin C-terminus deficient fibres in snorers and sleep apnea patients might render the muscle more vulnerable to high contraction stress." (PMID 30764835, 2019). "Cytoskeletal proteins desmin and dystrophin were morphologically evaluated in the uvula muscle of 22 patients undergoing soft palate surgery due to snoring and sleep apnea and in 10 healthy controls." (PMID 30764835, 2019). "Therefore, we aimed to investigate for desmin and dystrophin abnormalities in soft palate muscles of snoring and sleep apnea patients and to evaluate whether these abnormalities relate to deviations in swallowing function and severity of obstructive sleep apnea." (PMID 30764835, 2019). "Although the proportion of desmin and dystrophin abnormalities in sleep apnea patients were significantly higher than in controls, no relation to the severity of sleep apnea (AHI) could be established." (PMID 30764835, 2019).
speech disorder (1 paper, 2025). A term referring to disorders characterized by the disruption of normal speech. "Our analysis established that the prevalence of ID, ADHD, language and speech disorders increases when more dystrophin isoforms are affected, except for ASD." (PMID 41595432, 2025).
systemic amyloidosis (1 paper, 2021). "For example, screening for systemic amyloidosis in patients with gelsolin mutation, as well as cardiac and respiratory disease in patients with mutations in MYH7, DMD and LAMA2 genes." (PMID 34103343, 2021).
temporal lobe epilepsy (1 paper, 2016). A localization-related (focal) form of epilepsy characterized by recurrent seizures that arise from foci within the temporal lobe, most commonly from its mesial aspect. "Here, we aimed to study brain dystrophin distribution and expression in both, human and experimental temporal lobe epilepsy (TLE)." (PMID 27458343, 2016).
testicular disorder (1 paper, 2020). A non-neoplastic or neoplastic disorder affecting the testis. "The present study describes the first prenatally diagnosed 46,XX testicular disorders of sex development (46,XX testicular DSD) case with DMD gene mutation by integrated analyses in a Chinese pedigree." (PMID 32153624, 2020).
thyroid (1 paper, 2023). "Specifically, while DMD expression was higher in primary thyroid carcinoma compared to thyroid NAT, Dp427m expression there was lower compared to thyroid NAT, and the increase in overall DMD gene expression resulted from the elevated expression of Dp71b." (PMID 36900171, 2023).